MC4R (melanocortin 4 receptor)
Diseases named in the same sentence as MC4R in open-access papers (continued):
Sharing a sentence is not in itself a finding about the gene and the disease.
Obesity (continued). "This conclusion is supported by the data of other researchers on the close relationship between dysfunctions in the hypothalamic MC4R-melanocortin system and the development of obesity, insulin resistance and other metabolic abnormalities." (PMID 30870482, 2019). "Therefore, as the same mutations in the human MC4R gene are well recognized as an infrequent cause of obesity, it is credible that SNPs in this proximal minimal promoter region of the sheep MC4R could also contribute to the body weight and fat deposition traits of the sheep." (PMID 30634446, 2019). "An HF diet exacerbates obesity in Pomc, melanocortin-3 receptor (Mc3r), or melanocortin-4 receptor (Mc4r) knockout mice." (PMID 30997487, 2019). "Setmelanotide, an eight amino acid cyclic MC4R agonist peptide, is being investigated in several clinical studies for the treatment of obesity, including rare genetic disorders of obesity." (PMID 31100979, 2019). "GPCRs such as GLP1R, GHSR, and MC4R are popular pharmaceutical targets for diseases related to energy homeostasis, especially for obesity and diabetes." (PMID 31354618, 2019). "We identified six different novel variants within five obesity-related genes (SIM1, POMC, PCSK1, MC4R and LEPR) in seven out of 105 children with early-onset severe obesity in a Turkish population." (PMID 30991789, 2019). "Other than known syndromes associated with obesity, there are multiple monogenic forms of obesity which include LEP, LEPR, MC4R, and POMC1 majorly." (PMID 31070016, 2019). "Our data first suggest that SNPs in the rs2331841 site of the MC4R gene are closely related to obesity and its related metabolic disorders in Chinese Northern Han populations." (PMID 31781208, 2019). "Indeed, inactivation of either α-MSH precursor proopiomelanocortin or of MC4R lead inevitably to hyperphagia, increased preference for fat food, and obesity in genetically modified rodents and may underlie about 2% of genetic causes of obesity in humans." (PMID 30755592, 2019). "Setmelanotide, an MC4R agonist, is already undergoing a clinical trial for the treatment of obesity." (PMID 30503832, 2019). "In mice, targeted disruption of the MC4R gene has resulted in an obesity syndrome characterized by hyperphagia, hyperinsulinemia, hyperglycemia, and increasing growth without affecting the reproductive axes." (PMID 30634446, 2019). "Haploinsufficiency of MC4R produces massive obesity in humans, while haplo-inactivation of MC4R in mice results in hyperphagic obesity." (PMID 31124015, 2019). "The central hypothalamic melanocortin-4 receptor (MC4R) is a uniquely validated therapeutic target for the treatment of obesity based on both pharmacologic and human genetic evidence." (PMID 31100979, 2019). "Further efforts should also be undertaken at the molecular and cellular levels to investigate the mechanism of the MC4R gene on obesity." (PMID 31781208, 2019). "Newly available, targetted drugs will offer a novel therapeutic option for those patients with monogenic obesity due to MC4R or POMC dysfunction." (PMID 30991789, 2019). "Mutations leading to a reduced function of the melanocortin-4 receptor (MC4R) exert a major gene effect on extreme obesity." (PMID 31035493, 2019). "As a result, the feasibility of targeting the MC4R for treating obesity by peptides and small molecules ligands has been called into question, despite intense drug discovery and development activity which started in the 1990s." (PMID 31100979, 2019). "Obesity-related genes were retrieved in the Digsee database and the top 15 obesity-related genes were selected as disease genes (Adipoq, Igf1, Fto, Hsd11b1, Tnf, Gh1, Mc4r, Lep, Pparg, Il6, Crp, Lepr, Pomc, Lpl, and Ghr1)." (PMID 31060494, 2019). "Mc4r was shown to be involved in energy intake and expenditure and acts as a potential target for pharmacological intervention with obesity." (PMID 31024451, 2019).
Obesity (continued). "Overall, the anti-obesity effect of SDV in Mc4r−/− mice fits well with our view that the DMV serves as an important conduit of central melanocortin circuitry by which the brain conveys information to the periphery." (PMID 29545738, 2018). "The role of MC4R in obesity is well established based on both human genetic data and animal knockout models." (PMID 29991773, 2018). "The melanocortin-4 receptor (MC4R) is a potential drug target for treatment of obesity, anxiety, depression, and sexual dysfunction." (PMID 29910730, 2018). "Mouse models of obesity already suggest an involvement of AGRP in growth regulation through interaction with the melanocortin system especially the MC4R." (PMID 29843787, 2018). "Subjects/Methods: In two separate studies, we examined the efficacy of bilateral subdiaphragmatic vagotomy (SDV) with pyloroplasty in the prevention and treatment of obesity in Mc4r−/− mice." (PMID 29545738, 2018). "While obesity, as delineated through BMI measurements, is evident in homozygotes (yet not necessarily in heterozygotes) at early ages, the metabolic consequences of MC4R-related obesity appear in both heterozygotes and homozygotes only at later ages." (PMID 30068297, 2018). "Protein intake has been found to modify the effect of the MC4R gene on obesity-related traits, such as appetite and food craving." (PMID 29686896, 2018). "Whilst female mice overexpressing MRAP2 in PVN MC4R neurons demonstrate overt protection against obesity on a chow diet, this phenotype was only observed in male mice after challenge with high fat diet." (PMID 30352741, 2018). "We did not detect statistical associations between LEPR rs11371101, FTO rs9939609, MC4R rs2229616, and PPARG-2 rs1801282 polymorphisms and most obesity-related phenotypes and metabolic parameters." (PMID 29679223, 2018). "In the second study, the severe obesity that is characteristic of the adult Mc4r−/− genotype was significantly improved by SDV with a magnitude of 30% loss in excess BW over a 4-week period." (PMID 29545738, 2018). "Most studies have reported the associations between POMC, MC4R, and HNF4A variants and obesity and MetS-related phenotypes." (PMID 29598821, 2018). "We have used our whole exome sequencing data in 92,445 subjects to assess the role of MC4R C-terminus in human obesity and on receptor function." (PMID 29991773, 2018). "Data obtained from studying SDV as prevention and as a treatment strategy against Mc4r−/− mouse obesity demonstrates a robust anti-obesity effect." (PMID 29545738, 2018). "Based on these functional data we have determined a critical role of the C-terminus of MC4R in its trafficking, function and demonstrate a mechanistic link to human obesity." (PMID 29991773, 2018). "Even with the genetic burden of a MC4R LOF variant, the obesity phenotype is influenced by other genetic factors, both protective and deleterious, and environmental factors that contribute to BMI16,31–33." (PMID 29991773, 2018). "In testing the notion that the obesity rising from lesions of both the VMH and PVN is due to the loss of a common molecular substrate (i.e., the Mc4r), we assessed the impact of SDV on Mc4r deficient obese mice in two separate experiments." (PMID 29545738, 2018). "In this context, our identification of the interaction between GRP78 and MC4R provides a potential key signaling network to target as a treatment for hypothalamic ER stress and obesity." (PMID 30209265, 2018). "This study was intended to gain insight into the structure and specific ligand-binding properties of MC4R, a high-priority drug target for treating obesity." (PMID 29910730, 2018). "In line with the role of MC4R in satiety signaling and regulation of food intake, MC4R null mutant (MC4R −/−) mice develop severe obesity, while heterozygous (MC4R +/−) mice present a mildly obese intermediate phenotype." (PMID 30068297, 2018).
Obesity (continued). "The physiological relevance of the constitutive activity of MC4R in the context of obesity remains poorly understood." (PMID 30209265, 2018). "In fact, Mc4r and Adcy3 knockout mice exhibit similar phenotypes, including obesity and hyperinsulinemia." (PMID 29921800, 2018). "The resultant net result of suppressing this efferent vagal pathway would be a reduction in BW as evidenced previously by the weight-reducing effect of SDV in the VMH obesity syndrome, and at present by the Mc4r−/− obesity phenotype model." (PMID 29545738, 2018). "Several studies have examined the effect of obesity-risk genes, such as FTO, MC4R, and the transmembrane protein 18 (TMEM18) on GWG." (PMID 29686896, 2018). "MC4R expressed in the paraventricular nucleus has a critical role in the mechanisms of food intake, and the MC4R knockout mouse demonstrated the characteristics of being obesity, hyperphagia, and hyperinsulinemia." (PMID 28520814, 2017). "We identified the effect of MC4R rs12970134 on overweight/obesity and BMI, and we also found physical activity and sedentary behaviors modified the association between the rs12970134 and BMI in Chinese children and adolescents." (PMID 28081251, 2017). "BDNF is an important downstream mediator of MC4-R signaling, and its administration regulates the obesity in MC4-R knockout mice." (PMID 29062839, 2017). "We expectedly confirm an overall obesity-promoting effect of the FTO and MC4R minor-alleles in our study population." (PMID 28384342, 2017). "In order to see if the mitochondrial phenotype precedes heart failure as well as the Mc4r−/− obesity phenotype, the O2 consuming capacity of young lean Mc4r−/− myocardium was then analyzed using high-resolution respirometry." (PMID 28829041, 2017). "Here we have assessed gene-environment interaction effects of FTO and MC4R on obesity, taking into account any modulation due to age and gender." (PMID 28384342, 2017). "The conducted genome-wide analyses of obesity-related traits in pigs revealed prominent genetic factors like MC4R and BBS7 with known contributions to monogenic and polygenic causes in the etiology of obesity." (PMID 28831160, 2017). "Similar to MC4R mutation carriers, SIM1 mutation carriers also have early-onset obesity caused by increased appetite and food seeking behavior persisting into adulthood." (PMID 28472148, 2017). "SIM1 acts downstream of the melanocortin 4 receptor (MC4R), and mutations in this gene are a major cause of monogenic obesity in humans." (PMID 28472148, 2017). "MC4R agonists provide therefore a potential tool for the treatment of metabolic disorders as obesity." (PMID 28424580, 2017). "It is worth mentioning that only a small percentage of obesity cases are caused by mutations in single genes, such as leptin (LEP), leptin receptor (LEPR), and melanocortin 4 receptor (MC4R)." (PMID 28810876, 2017). "Gene variants in MC4R and FTO are associated with severe obesity and metabolic impairment in Caucasians." (PMID 28133617, 2017). "Here, we aim to determine the influence of the Mc4r gene on the liver of mice subjected to perinatal diet-induced obesity." (PMID 28930194, 2017). "In the previous study, the authors also described obesity-related traits in Mc4r-silenced mice fed a control diet; similar to what we have showed here in our study, there was overexpression of TGF-β and Col-1α compared to wild type mice." (PMID 28930194, 2017). "Agrp acts to increase appetite by binding to Mc4r, and overexpression of Agrp in transgenic mice led to obesity." (PMID 28480144, 2017). "Homozygous loss of MC4R function, and homozygous loss of proopiomelanocortin gene function, a preprohormone precursor of the endogenous MC4R agonist have both been reported in patients with early onset obesity." (PMID 28829041, 2017). "SNP rs17782313 mapped 188kb downstream of MC4R, which is well established as a candidate gene for obesity." (PMID 27926527, 2017).
Obesity (continued). "One of the numerous genes associated with human polygenic obesity is MC4R, encoding the melanocortin 4 receptor." (PMID 28755272, 2017). "Evidence also suggests that one of the MSH receptors, melanocortin 4 receptor (MC4R), is strongly linked with both weight regulation and APD-induced obesity." (PMID 28804444, 2017). "The present study attempts to provide an analysis of epidemiological and genetic data towards the possible mechanism of the role of MC4R or BDNF in obesity." (PMID 28396685, 2017). "The genetic variants near the Melanocortin-4 receptor gene (MC4R), a key protein regulating energy balance and adiposity, have been related to obesity and glucose metabolism." (PMID 28852042, 2017). "One study has revealed that common genetic variations near or in the MC4R contributes to obesity in American Indians." (PMID 27926527, 2017). "Obesity is a heritable disorder, and some of the many obesity susceptible genes are fat mass and obesity (FTO), leptin, and Melanocortin-4 receptor (MC4R)." (PMID 28924523, 2017). "Of note, none of the CpGs associated with BMI was near genes previously identified in GWASs of obesity-related traits, such as FTO (fat mass and obesity associated) or MC4R (melanocortin 4 receptor)." (PMID 28095459, 2017). "The MC4R homozygous knock-out mice had maturity onset obesity, hyperphagia, increased linear growth, hyperinsulinemia, and hyperglycemia, reduced metabolic rate." (PMID 28081251, 2017). "Specifically, major players like melanocortin 4 receptor (MC4R), leptin (LEP), and fat mass and obesity-associated gene (FTO) are known key regulators of feed intake/appetite and energy homeostasis." (PMID 28831160, 2017). "The mutated genes, related to obesity, include leptin (LEP), leptin receptor (LEPR), pro-opiomelanocortin (POMC) and melanocortin-4 receptor (MC4R)." (PMID 27894098, 2017). "Initially, the coding sequence of three candidate obesity genes, melanocortin-4 receptor (MC4R), agouti-related peptide (AGRP), and POMC, all part of the hypothalamic melanocortin pathway, was examined in 15 obese and 18 lean Labrador retrievers." (PMID 27157046, 2016). "The importance of MC4-Rs in control of body weight is illustrated by the presence of extreme obesity in MC4-R gene knockout mice and in humans with mutations in MC4-R." (PMID 27942392, 2016). "The current dominant screening for obesity identified single nucleotide substitutions in the Sim1 and Mc4r genes of obese pedigrees." (PMID 27585985, 2016). "In mammals, the melanocortin system plays an important role in regulating food intake and energy metabolism because disrupting melanocortin receptor-4 (MC4R) results in obesity, hyperphagia, and hyperglycemia in mice." (PMID 27853416, 2016). "Although the evidence regarding the effect of leptin on inflammatory response is controversial, we have confirmed our findings in other models of obesity such as db/db and melanocortin 4 receptor knock out mice." (PMID 27500833, 2016). "Mutations in the melanocortin 4 receptor (MC4R) gene, which codes for a G‐protein‐coupled receptor responsible for postprandial satiety signaling, have been associated with monogenic obesity." (PMID 26788538, 2016). "Compared with other obesity rat models, our Mc4r KO and DKO manifested a relatively earlier hyperglycaemia on a normal chow diet." (PMID 27713523, 2016). "The primary aim of this study was to investigate the association of obesity related SNPs (two FTO SNPs and one SNP near MC4R) with fetal growth throughout gestation in children of the Southampton Women's Survey (SWS)." (PMID 26907388, 2016). "Taken together, our study points towards the likelihood of MC4R-independent mechanisms and possibly MCR-independent pathways in the pathogenesis of MRAP2-associated obesity." (PMID 27106110, 2016).
Obesity (continued). "Future studies using high-resolution techniques have the potential to confirm the MC4-R deficiency phenotype in patients with interstitial 18q deletions encompassing MC4R and to characterize which genes downstream of MC4R modify the obesity phenotype." (PMID 27738543, 2016). "Highly-selective MC4R agonists BIM-22493 (RM-493) that cross the BBB when administered peripherally improved obesity, hyperinsulinemia and fatty liver diseases in DIO-mice." (PMID 28031898, 2015). "Nowadays, the use of MC4R-agonists in the treatment of metabolic disorders is confined to experimental models of obesity and MS." (PMID 28031898, 2015). "We have recently reported a novel rodent model of NASH using melanocortin 4 receptor-deficient (MC4R-KO) mice, which exhibit the sequence of events that comprise hepatic steatosis, liver fibrosis, and hepatocellular carcinoma with obesity-related phenotypes." (PMID 25816330, 2015). "Recently, the combined effect of FTO rs9939609 and MC4R rs17782313 has been discussed in relation to obesity, breast cancer and endometrial cancer." (PMID 26032905, 2015). "We assessed the efficacy of simultaneous agonism at the glucagon-like peptide-1 receptor (GLP-1R) and the melanocortin-4 receptor (MC4R) for the treatment of obesity and diabetes in rodents." (PMID 25652173, 2015). "Recently, we have reported that melanocortin 4 receptor-deficient (MC4R-KO) mice fed high-fat diet develop a liver condition similar to human NASH, which is associated with obesity, insulin resistance and dyslipidemia." (PMID 25816330, 2015). "Comparatively, Mc4r+/− mice display milder forms of obesity, with increased weight gain in response to high-fat diet, suggesting a gene-dosage effect." (PMID 25825681, 2015). "Mc4r−/− mice exhibit obesity, hyperphagia, hyperinsulinemia, hyperglycemia, and increased linear growth." (PMID 25825681, 2015). "Following the identification of obesity variants in FTO, a robust and replicated association between BMI and variants ~188 kb upstream of MC4R was reported [55, 58••, 85–87]." (PMID 26363598, 2015). "The lack of function of β-MSH reduces the amount of MSH peptide in the POMC/MC4R pathway, resulting in obesity." (PMID 25825681, 2015). "Genetic variation in the MC4R gene has been identified as responsible for monogenic forms of obesity." (PMID 24516669, 2014). "In KKAy mice with ectopic overexpression of agouti peptide, an endogenous melanocortin-4 receptor (MC4R) antagonist, social isolation promotes obesity due to the primary decreased energy expenditure and secondary increased food consumption." (PMID 24804243, 2014). "Three genes, MC4R, LEP and POMC, have been identified through genetic association to confer an increase in obesity susceptibility and are also environmentally responsive to dietary intake." (PMID 25127133, 2014). "Here, we report the effects of the MC4-R-selective peptide agonist MC4-NN1-0182 on obesity in DIO rats and DIO minipigs." (PMID 24204009, 2014). "Studies of severe and common forms of obesity have demonstrated that the Melanocortin-4 Receptor (MC4R) is an important regulator of obesity and adiposity." (PMID 24820477, 2014). "Overall, our observations identify MC4-R agonism as a viable target for the treatment of obesity and possibly also the insulin resistance which is a central factor involved in the pathogenesis of type 2 diabetes." (PMID 24204009, 2014). "Taken together, these findings indicate that MC4R signaling strongly modulates D1R signaling, making it an interesting target for pharmacotherapies to combat psychopathologies such as addiction and obesity." (PMID 24723856, 2014).